CHPF (chondroitin polymerizing factor)
Diseases named in the same sentence as CHPF in open-access papers (continued):
Sharing a sentence is not in itself a finding about the gene and the disease.
gastric cancer (continued). "Additionally, E2F1 was identified as a potential downstream target of CHPF in the regulation of gastric cancer, and its knockdown decreased the CHPF-induced promotion of gastric cancer." (PMID 34564711, 2021). "Therefore, our current study is the first to reveal the expression pattern and functions of CHPF in gastric cancer." (PMID 34564711, 2021). "On the basis of these results, one could conclude that CHPF may promote the development of gastric cancer through the regulation of E2F1." (PMID 34564711, 2021). "Moreover, the results of the wound-healing assay were consistent with those of the Transwell assay, in which the migration ability of gastric cancer cells appeared to be promoted by CHPF overexpression (P < 0.001)." (PMID 34564711, 2021). "Furthermore, it was also clarified that the effects of CHPF overexpression on the proliferation, colony formation, apoptosis, and migration of gastric cancer cells was significantly alleviated by the simultaneous knockdown of E2F1." (PMID 34564711, 2021). "Further investigations showed that CHPF may promote the proliferation, colony formation, and migration and inhibit the apoptosis of gastric cancer cells through the regulation of E2F1." (PMID 34564711, 2021). "Moreover, survival curves according to the Kaplan-Meier analysis indicated relatively poorer prognosis of patients with higher CHPF expression (log-rank P < 0.05), which was consistent with the data mining result of the gastric cancer database in KM plotter." (PMID 34564711, 2021). "Moreover, further investigation revealed that CHPF could promote proliferation and migration, and inhibit apoptosis of gastric cancer cells through the regulation of E2F1." (PMID 34564711, 2021). "Therefore, CHPF may act as an oncogene-like protein and serve as a prognostic indicator and therapeutic target in gastric cancer treatment." (PMID 34564711, 2021). "Thus, the inhibition of gastric cancer development by CHPF knockdown was proven in vivo." (PMID 34564711, 2021). "E2F1 was a target of chondroitin polymerizing factor (CHPF), and silencing of E2F1 abolished CHPF-induced growth and migration in gastric cancer." (PMID 40221814, 2025). "More importantly, a recent study emphasized that CHPF is able to regulate the expression of E2F1 through UBE2T‐mediated ubiquitination, thus promoting gastric cancer development." (PMID 38775031, 2024). "Furthermore, in gastric cancer, E2F1 was a potential downstream target of CHPF, and knockdown of E2F1 reduced the CHPF-induced promotion of gastric cancer." (PMID 40070576, 2025). "Lentiviruses expressing shCHPF (designed for CHPF knockdown) or shCtrl (used as a negative control) were used to transfect the human gastric cancer cell lines AGS and SGC-7901." (PMID 34564711, 2021). "Despite all this research progress, cancer-related studies of CHPF are still rare, and the relationship between CHPF and gastric cancer has not yet been established." (PMID 34564711, 2021). "However, the role of CHPF in gastric cancer has not been reported until now and remains largely unknown." (PMID 34564711, 2021). "However, the relationship between CHPF and gastric cancer has not been fully investigated." (PMID 34564711, 2021). "CPXM2 and CHPF have not been reported in CRC, but have been found to promote gastric cancer progression." (PMID 38654221, 2024).
hepatocellular carcinoma (4 papers, 2014 to 2023). A malignant tumor that arises from hepatocytes. "Here we showed that CHPF was frequently downregulated in hepatocellular carcinoma (HCC) tumors compared with adjacent non-tumor tissues, and its downregulation was associated with poor overall survival." (PMID 33809195, 2021).
lung cancer (3 papers, 2020 to 2024). A malignant neoplasm involving the lung. "CHPF mRNA levels were then assessed in lung cancer cell lines including A549, 95-D, NCI-H1299, H1688, and NCI-H460 by qRT-PCR." (PMID 32348423, 2020). "The in vivo study revealed that CHPF contributed to the tumorigenicity of lung cancer cells in xenograft mouse models." (PMID 32348423, 2020). "In summary, we found that the expression of CHPF in lung cancer tissues was higher than that in normal lung tissues." (PMID 32348423, 2020). "In this study, to investigate the function of CHPF in lung cancer, lentiviral vectors expressing CHPF shRNA were stably transduced into A549 and H1299 cells." (PMID 32348423, 2020). "To evaluate the role of CHPF in lung cancer metastasis, we assessed the effects of CHPF silencing in A549 and H1299 cells." (PMID 32348423, 2020). "The TCGA database indicates that chondroitin polymerizing factor (CHPF) is overexpressed in human lung cancer tissues compared with normal tissues and this overexpression corresponds to shorter overall survival in lung cancer patients." (PMID 32348423, 2020). "CHPF was found to promote lung cancer cell proliferation, migration, and invasion in vitro and tumorigenesis in vivo." (PMID 32348423, 2020). "In this study in vitro, we found that CHPF silencing inhibited proliferation and colony formation and promoted cellular apoptosis in lung cancer cells." (PMID 32348423, 2020). "Through the analysis of the datasets from TCGA, it was found that, compared with human normal tissues, lung cancer tissues had significant overexpression of CHPF mRNA." (PMID 32348423, 2020). "In this study, we demonstrated elevated expression of CHPF mRNA in lung cancer tissues and five lung cancer cell lines." (PMID 32348423, 2020). "An in-depth knowledge of the molecular mechanism and related signaling pathways that govern CHPF activity may be of benefit in lung cancer treatment." (PMID 32348423, 2020). "Elevated CHPF expression corresponded to shorter overall survival in lung cancer patients." (PMID 32348423, 2020). "This highlighted CHPF as a potential therapeutic target for the clinical treatment of lung cancer." (PMID 32348423, 2020). "Moreover, CHPF silencing was also demonstrated to reduce lung cancer cell migration and invasion." (PMID 32348423, 2020). "However, the function of CHPF in human lung cancer has remained undefined." (PMID 32348423, 2020). "In their investigation, the researchers additionally noted an elevation in CHPF expression in non‐small cell lung cancer (NSCLC) and underscored the suppressive consequences of CHPF suppression on cellular proliferation, apoptosis and cell cycle progression." (PMID 38775031, 2024). "However, the mechanism of high CHPF expression in lung cancer development and progression has not been studied in detail." (PMID 32348423, 2020).
malignant melanoma (3 papers, 2020 to 2023). "Moreover, CHPF can promote the tumorigenicity of malignant melanoma by regulating CDK1." (PMID 33809195, 2021). "However, the relationship between CHPF and malignant melanoma (MM) is still unknown." (PMID 32612115, 2020).
metastatic tumors (2 papers, 2015 to 2021). "In line with the in vitro results, we found that CHPF overexpression significantly reduced the number of metastatic tumors on the lung surface." (PMID 33809195, 2021). "Interestingly, none of the changes in these transcripts in metastatic tumors were significant, except for CHPF (p = 0.04), the only gene not altered in non-metastatic tumors which appeared overexpressed around 3 fold." (PMID 26482785, 2015).
breast tumor (1 paper, 2022). "Because of the unequal number of TCGA-BRCA tumor samples and normal samples, a paired analysis was selected, which showed a significant increase in CHPF gene expression levels in breast tumor samples." (PMID 35372047, 2022).
endometriosis (1 paper, 2023). The growth of functional endometrial tissue in anatomic sites outside the uterine body. "At present, most studies focus on the function of CHPF in cancers, and little has been studied in endometriosis." (PMID 36930359, 2023).
liver cancer (1 paper, 2021). An epithelial or non-epithelial malignant neoplasm that arises from the liver. "In the present study, we evaluated the expression of CHPF using Western blotting and immunohistochemistry in HCC cases treated at a local hospital and using a commercial human liver cancer tissue microarray." (PMID 33809195, 2021).
cancer (13 papers, 2015 to 2026). A tumor composed of atypical neoplastic, often pleomorphic cells that invade other tissues. "The association between CHPF transcript expression/DNA methylation and cancer immune infiltration and immune markers was investigated using the TIMER and TISIDB databases." (PMID 35372047, 2022). "Furthermore, aside from its involvement in CS biosynthesis, CHPF has been associated with diverse human cancers." (PMID 38775031, 2024). "Several recent studies have reported that CHPF is associated with cancer progression." (PMID 33809195, 2021). "The interaction network of CHPF with the identified cancer associated genes was then assessed." (PMID 32348423, 2020). "The ECM-receptor interaction and PI3K-AKT pathways are cross-linked with each other and consist of many genes involved in cell motility and cancer metastasis, which is consistent with the metastasis-promoting role of CHPF genes." (PMID 35372047, 2022). "Although such a tumor-promoting role of CHPF in certain types of cancer has been proposed, the direct effects of CHPF-modified CS have not yet been examined." (PMID 33809195, 2021). "The similarly up-regulated chondroitin synthases (CHSY1, CHSY3, and CHPF) in both cancer tissue and human placenta indicate an important role of the proteoglycan CS chains length for Plasmodium falciparum VAR2CSA protein binding." (PMID 34966741, 2021). "We evaluated the correlation between clinicopathological parameters and expression of CHPF in HCC patients and explored the potential molecular mechanisms underlying its action during cancer progression." (PMID 33809195, 2021). "We found that three chondroitin synthases (CHSY1, CHSY3, and CHPF) were upregulated in both cancer tissue and placenta, indicating an important role of ofCS chains length for VAR2CSA binding." (PMID 34966741, 2021). "Chondroitin polymerizing factor (CHPF) plays an important role in the development of certain malignant tumors." (PMID 33301643, 2021). "CHPF silencing markedly downregulated the mRNA expressions of six cancer genes at the transcriptional level." (PMID 32348423, 2020). "Although the functional research of CHPF is still in the initial stage, its role in the development of some types of human cancers has been revealed." (PMID 32612115, 2020). "It has been reported that co-expression of CHSY3 with CHPF confers a chondroitin sulfate polymerization activity, and chondroitin sulfate plays an important role in cancer biology." (PMID 26515597, 2015). "Moreover, analysis of the IPA disease and function database highlighted cancer as the most relevant disease regulated by CHPF." (PMID 38775031, 2024). "We reason that the expression of PGs in different cancer types may govern the influence of CHPF on cancer cells." (PMID 33809195, 2021). "CHPF, which is abnormally expressed in human cancer, can act as a potential tumor promoter." (PMID 34564711, 2021). "Three chondroitin synthases (CHSY1, CHSY3, and CHPF) were upregulated in both cancer and placenta, indicating the length of ofCS chains might be an important factor for VAR2CSA binding." (PMID 34966741, 2021). "Previous studies have indicated that CHPF is frequently upregulated in certain cancer types, and it may have cancer-promoting functions." (PMID 33809195, 2021). "CHPF is located in the 2q35-q36 region of human chromosomes, spanning four exon regions, and plays an important role in cellular function.The latest study reported that, CHPF may act as both an oncogene and a cancer-promoting factor in a variety of tumors." (PMID 35372047, 2022). "Chondroitin Polymerizing Factor (CHPF), is an enzyme involved in chondroitin sulfate (CS) elongation and a novel key molecule in the poor prognosis of many cancers." (PMID 35372047, 2022). "Intriguingly, we discovered that CHPF displays tumor suppressing functions in HCC cells, which is different from other types of cancer cells." (PMID 33809195, 2021).
cancer (continued). "A recent study on CHPF in HCC reported high CHPF expression in 45% (35/77) of HCC cases and low CHPF expression in all para-carcinoma tissues, which was observed using immunohistochemistry." (PMID 33809195, 2021). "Currently, there is no clear mechanism of action of CHPF in cancer." (PMID 35372047, 2022). "The results obtained demonstrate that CHPF is highly expressed in BRCA, and may act as a cancer promoter to increase cell viability and invasiveness by regulating matrix metallopeptidase 2 (MMP2) expression and epithelial‐mesenchymal transition (EMT)‐related proteins." (PMID 33301643, 2021). "However, there is a lack of more studies about the emerging molecular marker, CHPF, in cancer." (PMID 35372047, 2022).
tumor (8 papers, 2020 to 2024). "Through analysis of the prognosis of 876 patients in the KM plotter database, the association between high CHPF expression and T infiltrate, advanced tumor stage and poor survival rate was determined." (PMID 34564711, 2021). "Little has been reported about CHPF as a novel tumor-associated gene." (PMID 35372047, 2022). "The results revealed a significant elevation in CHPF expression in tumour tissues compared to normal tissues (p < 0.001)." (PMID 38775031, 2024). "Analysis of gene expression profiling data from The Cancer Genome Atlas (TCGA) further validated the upregulation of CHPF in CRC tumour tissues (p < 0.001)." (PMID 38775031, 2024). "CHPF demonstrated upregulation in CRC tumour tissues, and its increased expression was associated with higher tumour malignancy grades." (PMID 38775031, 2024). "In conclusion, our study demonstrated that CHPF, a novel tumor-promoting gene in BRCA, can promote cell migration and invasion through the ECM and PI3K/AKT signaling pathways, ultimately altering the survival of BRCA patients." (PMID 35372047, 2022). "Taken together, our results suggest that CHPF is frequently downregulated in HCC, and that this downregulation is associated with advanced tumor stages and poor survival chances in HCC patients." (PMID 33809195, 2021). "The results showed that high CHPF expression was correlated with increased Tumor cell infiltration and advanced tumor stage, which was further confirmed by Spearman rank correlation analysis." (PMID 34564711, 2021). "Immunohistochemistry revealed that dot-like precipitates of CHPF mainly occurred in the cytoplasm of adjacent non-tumor hepatocytes but were rarely observed in the surrounding stromal cells and bile duct cells." (PMID 33809195, 2021). "The results indicated that CHPF was downregulated in HCC tissues compared to non-tumor liver specimens." (PMID 33809195, 2021). "The expression level of CHPF in tumor tissues was also generally upregulated, as shown by the statistical analysis (P < 0.001)." (PMID 34564711, 2021). "Univariate analysis demonstrated that CHPF expression, pathologic stage, ‐tumor (T), ‐M and ‐node (N), and age were all related to the overall survival for patients with BRCA (P < 0.05)." (PMID 33301643, 2021). "The results indicated that CHPF protein levels were significantly downregulated in the tumor tissues, compared to their non-tumor counterparts (Paired t-test, p = 0.032)." (PMID 33809195, 2021). "Our results consistently indicated that CHPF is frequently downregulated in tumor tissues, compared to the case for the adjacent non-tumor liver tissues." (PMID 33809195, 2021). "In conclusion, our study showed, as the first time, CHPF as a tumor promotor for MM, whose function was carried out probably through the regulation of CDK1." (PMID 32612115, 2020). "In vitro and in vivo detection demonstrated that CHPF acts as a tumor promoter in MM, probably through the regulation of CDK1." (PMID 32612115, 2020). "In line with the potential tumor promotion effect of CHPF indicated by the detection of tissues, the over-expression of CHPF promoted the cell proliferation and colony formation ability and simultaneously inhibited cell apoptosis." (PMID 32612115, 2020). "In this work, our studies revealed that CHPF acts as a tumor promoter for the development and progression of MM." (PMID 32612115, 2020). "Collectively, these findings suggest that CHPF may act as a tumour promoter in CRC, operating in a VEGFB‐dependent manner and could be a potential target for therapeutic interventions in CRC treatment." (PMID 38775031, 2024). "Relationship between CHPF expression and tumour characteristics in patients with CRC." (PMID 38775031, 2024). "Moreover, decreased CHPF expression was correlated with advanced tumor stages (Fisher’s exact test; p = 0.0202)." (PMID 33809195, 2021).
tumor (continued). "Immunostaining of excised tumor sections revealed a decrease in the proportion of Ki67-positive cells in CHPF-overexpressing tumor tissues, indicating that CHPF may modulate HCC cell proliferation." (PMID 33809195, 2021). "Moreover, the results from in vivo experiments demonstrated that tumor growth was suppressed by CHPF knockdown." (PMID 34564711, 2021). "Moreover, the suppression of MM tumor growth by CHPF knockdown was further illustrated by mice xenograft model in vivo." (PMID 32612115, 2020). "In addition, following the verification of CHPF expression in xenograft tumors by qPCR, Ki-67 index was also detected by IHC analysis, which showed a significant downregulation in shCHPF group and was in line with the inhibited tumor growth." (PMID 32612115, 2020). "Furthermore, statistical analysis was performed to analyze the relationship between CHPF expression and tumor characteristics of MM patients, which showed that high CHPF expression was positively related with more advanced T stage, with a Pearson correlation coefficient of 0.226 (P < 0.05)." (PMID 32612115, 2020). "Our results revealed a significant upregulation of CHPF expression in CRC tumour tissues compared to normal tissues, with its levels correlating with tumour malignancy." (PMID 38775031, 2024). "We detected significant downregulation of IRS2 and NT5E in tumor tissues, whereas CACNA1H, CHPF, SDC1 and ATP6AP1 were highly expressed in tumor tissues than in normal tissues." (PMID 36277284, 2022). "We first analyzed the mRNA levels of CHPF in human BRCA based on TCGA database and observed a significant increase of CHPF expression in tumor tissues compared to normal adjacent breast tissues (P < 0.01)." (PMID 33301643, 2021). "This not only implies a pathophysiologic role of CHPF in HCC cells, but also suggests significance of abnormal CS during HCC tumor progression." (PMID 33809195, 2021). "To investigate the effects of CHPF on tumor growth in vivo, we subcutaneously transplanted CHPF-overexpressing Hepa1-6 cells and control cells into NOD/SCID mice, and CHPF overexpression significantly decreased tumor weight and volume." (PMID 33809195, 2021). "We demonstrate that the chondroitin polymerizing factor (CHPF), an enzyme that mediates the elongation of chondroitin sulfate (CS), is a critical elicitor of the malignant characteristics of HCC as it modifies the potent tumor suppressor, decorin (DCN)." (PMID 33809195, 2021). "Taken together, these data suggest that CHPF contributes to BRCA cell proliferation, invasion and migration and may act as a tumor promoter in BRCA." (PMID 33301643, 2021). "In addition, a mouse xenograft model constructed with SGC-7901 cells with or without CHPF knockdown was used to conduct in vivo experiments where the impaired tumor growth and downregulated expression of Ki-67 by CHPF knockdown were illustrated." (PMID 34564711, 2021). "However, as far as we know, the expression of CHPF in BRCA and its role in tumor progression are not clear." (PMID 33301643, 2021).